BCR (BCR activator of RhoGEF and GTPase)
Diseases named in the same sentence as BCR in open-access papers (continued):
Sharing a sentence is not in itself a finding about the gene and the disease.
COVID-19 (20 papers, 2020 to 2025). A disease caused by infection with severe acute respiratory syndrome coronavirus 2. "Our results demonstrate that COVID-19 suppresses the immune activity and consequentially elevates the level of BCR-ABL P210 of CML patients." (PMID 39635534, 2024). "To validate this finding and extend it to a larger number of subjects, we retrieved BCR repertoire datasets from COVID-19 diagnosed subjects from the AIRR Data Commons by querying the iReceptor Gateway, together with healthy controls." (PMID 39058741, 2024). "Our results indicate that COVID-19 suppresses immune activity and leads to an increase in the level of BCR-ABL P210 among CML patients." (PMID 39635534, 2024). "To further verify the role of COVID-19 regarding the increase in BCR-ABL P210 level, we next isolated PBMCs from CML patients and infected them with a SARS-CoV-2 pseudovirus." (PMID 39635534, 2024). "It is necessary to increase the number of samples from CML patients to further verify the difference in BCR-ABL P210 levels after contracting COVID-19." (PMID 39635534, 2024). "As expected, the diversity of BCR clones is significantly lower in COVID-19 patients compared with controls." (PMID 37153628, 2023). "Here, in contrast to previous reports, we were able to stratify COVID-19 patients and healthy individuals based on shared clusters of BCR sequences." (PMID 37153628, 2023). "To assess changes in BCR repertoires of COVID-19 patients, we collected 79 blood samples and sequenced their BCR repertoires." (PMID 37153628, 2023). "In further support of this, the degree of class-switching, inferred from the BCR sequencing data, was significantly elevated between IgD/M and IgG1 and IgA1 and finally to IgG2 in COVID-19 patients." (PMID 35216673, 2022). "First, in COVID-19 patients, we observed increased BCR complementarity-determining region 3 (CDR3) lengths compared to sepsis; such increases have been associated with antibody polyreactivity and autoimmunity." (PMID 35216673, 2022). "Previous reports indicate an unexpectedly high level of BCR convergence between unrelated COVID-19 patients." (PMID 35216673, 2022). "We assembled a total of 74,634 BCR groups from all 16 COVID-19 patients, with each group representing a potential B cell clonal expansion event." (PMID 33237441, 2021). "Next, to reveal the unique gene patterns and preferences of BCR or TCR in recovered COVID-19 patients, we compared the usage rate of immunoglobulin variable (V) genes." (PMID 35046942, 2021). "Compared to healthy individuals, COVID-19 patients showed significantly lower BCR diversity, indicating widespread B cell clonal expansions upon likely antigen recognition." (PMID 33237441, 2021). "Compared to controls, asymptomatic and mildly ill patients, severely sick COVID-19 patients showed lower BCR diversity." (PMID 35095917, 2021). "Our sequencing data also included scTCR-seq and scBCR-seq dataset to investigate the characteristics of TCR/BCR immune repertoires in recovered COVID-19 patients." (PMID 35046942, 2021). "CD21 (complement receptor type 2, CR2), a co-receptor of the BCR, was also significantly down-regulated in severe COVID-19 patients." (PMID 32669287, 2020). "Next, to reveal the unique gene patterns and preferences for BCR or TCR in the COVID-19 patients, we compared the usage of V(D)J genes among the participants." (PMID 32796814, 2020). "To identify convergent antibodies for COVID-19, we pooled the BCR data from the 14 individuals together and carried out clonal grouping using Change-O toolkit, based on common genes of IGHV and IGHJ and nucleotide similarity of CDR3 sequences." (PMID 32796814, 2020). "The scores of the known antibodies were higher than those came from whole repertoires of control patients as well as most of the COVID-19 infected repertoires, suggesting that these coefficients are meaningful not only for the repertoire level, but also for single BCR sequences." (PMID 37153628, 2023).
COVID-19 (continued). "Therefore, another central part of our study is to assess the repertoire diversity of TCR and BCR and especially their clustering, enabling us to deduce COVID-19-relevant TCR or BCR signatures." (PMID 34531370, 2021). "In silico prediction of the specificity of BcR IG clonotypes resulted in the identification of 764 unique SARS-homologous clonotypes within the BcR IG gene repertoires of 66 (81.5%) of 81 individuals who tested positive for COVID-19 during the first pandemic wave." (PMID 40489958, 2025). "While asymptomatic COVID-19 patients displayed more abundant TCR diversity, on the contrary, they showed less BCR clonal expansion compared to moderate and severe patients." (PMID 34531370, 2021). "In this study, we profiled adaptive immune cells of PBMCs from recovered COVID-19 patients with varying disease severity using single-cell RNA and TCR/BCR V(D)J sequencing." (PMID 32796814, 2020). "We revealed that COVID-19 could inhibit immune activity by decreasing the number of effectors (CD8+ T cells) and increasing the number of Treg cells, which correlated with an elevated BCR-ABL P210 level." (PMID 39635534, 2024).
Autoimmunity (19 papers, 2013 to 2026). The occurrence of an immune reaction against the organism's own cells or tissues. "The rs2476601/PTPN22(G/A) SNP is a functional missense variant that dampens TCR/BCR signaling, thusimpacting autoimmunity by increasing the number of autoreactive T and B cells thatevade central tolerance." (PMID 40261241, 2025). "Genome-wide association studies have also identified the BCR signaling among the most frequent genetic polymorphisms predisposing to autoimmunity." (PMID 38571942, 2024). "Here, we examined the effect of impaired pre-BCR selection on plasma cells (PCs) using a model of autoimmunity characterised by elevated serum autoantibody levels." (PMID 42095480, 2026). "Anergic B cells remain in the periphery but are unresponsive to BCR stimulation; however, failure to maintain the anergic state can result in autoimmunity and lymphoproliferation." (PMID 36619973, 2023). "BTK regulates the function of B cells in host defense and autoimmunity by participating in the BCR signaling pathway." (PMID 37638060, 2023). "Ikaros plays a role in preventing autoimmunity by administering BCR unresponsiveness and repressing TLR signaling transduction." (PMID 34950704, 2021). "The low threshold of BCR activation, the numerous effector functions of MZ B cells and the link between autoimmunity, TLS and MZ lymphoma development in pSS suggests a direct involvement of this population in TLS pathology." (PMID 30258435, 2018). "ABC identified in models of autoimmunity are dependent on BcR, TLR-7, and TLR-9 stimulation, and memory ABC populations are implicated in mediating autoimmunity." (PMID 29632538, 2018). "Equally, excessive IL‐21 production could result in the potentially detrimental lowering of BCR or CD40 signaling thresholds and/or exaggerated B cell expansion and thus predispose to autoimmunity." (PMID 35801309, 2022). "These previous data were, however, mainly acquired in the context of autoimmunity, where B cells receive a multitude of different signals and IFNγ signaling seems primarily to synergize with BCR-, CD40- and TLR-mediated stimuli to induce spontaneous germinal centers." (PMID 35187121, 2022). "For lymphocytes in healthy subjects, the Ikaros protein family exerts different effects on the growth, reproduction, and differentiation of many kinds of innate or adaptive lymphocytes in vivo and prevents autoimmunity by administering BCR unresponsiveness and repressing TLR signaling transduction." (PMID 34950704, 2021). "In support of this, and relevant to our studies here showing a role for SLAMF7 expression on B cells in the setting of neuro-autoimmunity, a recent study has shown that SLAMF7 signaling on B cells is inhibitory and antagonizes BCR activation." (PMID 36199066, 2022). "Hereby, the aberrant expression of survival factors and chemokines would support clonal expansion in the absence of BCR editing and support persistence of autoimmunity." (PMID 30258435, 2018). "Rather, it was found that the presence of non-secreted auto-antibodies at the surface of B-cells (the BCR) is critical, suggesting that it is the APC function of B-cells which is key for autoimmunity." (PMID 38571942, 2024).
melanoma (19 papers, 2011 to 2024). A malignant, usually aggressive tumor composed of atypical, neoplastic melanocytes. "Decreased BCR gene segment diversity was associated with improved survival in melanoma." (PMID 39530091, 2024). "Decreased BCR gene segment diversity was associated with improved survival in melanoma (HR = 2.67)." (PMID 39530091, 2024). "Importantly, BCR diversity was lower (i.e. increased clonality) and SHM was higher in primary tumour and regional subcutaneous metastases compared with distant metastases and decreased BCR diversity was associated with better survival in melanoma." (PMID 35218154, 2022). "The effect of BCR on ICI activity has primarily been investigated in melanoma cohort‐related studies." (PMID 39509319, 2024). "In general, these findings demonstrated that our six IAG signature not only played a critical role in stratifying melanoma patients and predicting OS but also was significantly connected with ICB immunotherapy, BCR/TCR richness, immune cell populations, and immune checkpoints." (PMID 33688507, 2021). "For instance, clonal counts for both immunoglobulin heavy and light chains as well as BCR diversity were increased in the responders than those in the non-responders of melanoma patients upon neoadjuvant ICI therapy." (PMID 34899709, 2021). "Just as pimozide shows enhanced efficacy in CML when combined with BCR/ABL inhibitors, pimozide may be particularly useful in melanoma when combined with BRAF inhibitors." (PMID 21680956, 2011). "However, the pattern of Swiprosin-1 expression is regulated by various signaling pathways such as PKC-βI/η in HMC-1 mast cells, PKC-θ and NF-κB in Jurkat T cells, BCR in WEHI231 B cells, RANK-L in osteoclast-like cells and EGF in melanoma B16F10 cells, and PKC-β in glomerular endothelial cells." (PMID 30405162, 2018).
autoimmune disease (18 papers, 2013 to 2025). A disorder resulting from loss of function or tissue destruction of an organ or multiple organs, arising from humoral or cellular immune responses of the individual to their own tissue constituents. "On the contrary, the DN2 subset has been shown to be dominant in autoimmune diseases, and has been associated with exhausted or dysfunctional cells, due to the expression of inhibitory receptors of BCR signaling." (PMID 36717688, 2023). "For diagnostic purposes, BCR sequences unique to the infectious or autoimmune diseases could be detected from the BCR repertoire constructed with an acceptable range of PB volume." (PMID 35866358, 2022). "Abnormalities in BCR signaling could shape the splenic B-cell populations and predispose to autoimmune disease." (PMID 23914190, 2013). "BTK is required for synergistic cytokine response by TLR9 and BCR in human and murine B cells, with implications in B cell activation and autoimmune diseases." (PMID 40980882, 2025). "By collecting these BCR repertoires into an accessible database, we hope to also enable comparative analysis of patient repertoires in pSS and potentially other autoimmune disorders." (PMID 38454506, 2024). "In autoimmune diseases, aAgs are common intracellular molecules that B cells (via BCR recognition) and Abs cannot access under normal conditions." (PMID 36765855, 2023). "NGS is being increasingly used to profile this repertoire of TCR and BCR clonotypes and measure T- and B cell dynamics in healthy individuals, patients with cancer, infections, and autoimmune diseases." (PMID 35022065, 2022). "PD-1 also inhibits BCR-mediated B cell activation and proliferation, which leads to the prevention of autoimmune diseases." (PMID 32256500, 2020). "As presented here, most of the studies to date on BCR sequencing in autoimmune diseases are limited by small numbers of patients." (PMID 29574826, 2018). "Since Syk and Btk showed important regulation of both BcR and FcR signaling, specific pharmacological inhibitors for these kinases are currently undergoing preclinical and clinical trials as treatment for autoimmune diseases and hematological cancers." (PMID 24795896, 2014). "The interaction between CCR2 and BCR may contribute to exploring the mechanism of autoimmune diseases." (PMID 35875970, 2022). "For instance, identifying clonal lineage in BCR repertoires (BCR clonal lineage grouping) is generally the starting point for several studies involving distinct clinical contexts like autoimmune diseases, allergy, cancer, ageing, and immune responses to infections." (PMID 36037250, 2022). "The decreased TCR or BCR diversity has been observed in cancers and autoimmune diseases, which may contribute to the development of the diseases." (PMID 29628928, 2018). "BCR sequencing in the context of autoimmune diseases is therefore both timely and essential." (PMID 29574826, 2018). "The co-engagement of TLR7 and BCR has been shown to promote autoreactive B cell activity indicating that this could contribute to disease symptoms in autoimmune diseases." (PMID 24740301, 2014). "BCR signaling significantly influences B cell-mediated autoimmune inflammation, suggesting that inhibiting BCR signaling could emerge as a novel treatment approach for autoimmune diseases." (PMID 40406113, 2025).
myeloid neoplasm (18 papers, 2013 to 2026). Proliferation of myeloid cells originating from a primitive stem cell. "CML is a myeloid neoplasm caused by the BCR-ABL fusion gene that causes dysregulated cellular proliferation and apoptosis resistance via interference in downstream signaling pathways." (PMID 35091542, 2022). "We identified upregulation of Dnmt1 as a consequence of BCR-ABLp210, and we show that HSPC-restricted expression of Dnmt1 in transgenic mice is sufficient to phenocopy the BCR-ABLp210-associated DNA methylation changes and induce myeloid malignancies." (PMID 29955131, 2019). "Genetic testing confirmed an uncommon BCR::PDGFRA and coexisting PDGFRA mutations (c.1666G>A and c.1701A>G), confirming the diagnosis of myeloid neoplasm with BCR::PDGFRA rearrangement." (PMID 41783439, 2026). "In other words, Blk is involved in signaling by both JAK2V617F and BCR-ABL in two different types of myeloid malignancies." (PMID 41226393, 2025). "AML with BCR/ABL1+ had been included as a separate provisional entity in 2016 by WHO classification of myeloid neoplasms." (PMID 37234472, 2023). "In 2016, WHO has included AML with BCR/ABL1+ gene as a separate provisional entity in its latest classification of myeloid neoplasms." (PMID 37234472, 2023). "Considering all levels of evidence, the patient was diagnosed as myeloid tumor with BCR-PDGFA rearrangement." (PMID 35713428, 2022). "Here, we report a rare case of myeloid neoplasm with BCR-PDGFRA rearrangement characterized by obvious elevation of leukocyte count and megalosplenia." (PMID 35713428, 2022). "We tested the FIP1L1/PDGFRA and BCR/ABL fusion genes to exclude the possibility of a myeloid neoplasm or clonal eosinophilia." (PMID 33916211, 2021). "Together, these data show that HSPC-restricted expression of Dnmt1 is sufficient to phenocopy the DNA hypomethylation phenotype induced by BCR-ABLp210 expression in the same compartment and to promote the development of myeloid malignancies." (PMID 29955131, 2019). "Evidence for BCL2 inhibition in this setting is limited to anecdotal reports, including a recent case describing prolonged disease control with ruxolitinib plus venetoclax in a BCR::JAK2-rearranged myeloid neoplasm, suggesting potential synergistic activity of JAK2 and BCL2 blockade." (PMID 41530508, 2026). "The therapeutic effect of imatinib on Myeloid neoplasm with BCR-PDGFRA rearrangement." (PMID 35713428, 2022). "Accordingly, the diagnosis of myeloid neoplasm with BCR-PDGFA rearrangement was confirmed." (PMID 35713428, 2022). "Moreover, recent knock-in models of BCR-ABL and FLT3-ITD (a third tyrosine kinase associated with myeloid malignancies) have both been shown to compromise HSC self-renewal in transplantation experiments." (PMID 23750118, 2013). "All patients with concurrent presence of BCR::ABL1 and JAK2 V617F (JAK2 V617Fpos/BCR::ABL1pos) gave written informed consent to be included in the German Registry of Eosinophils, Mast Cells and rare myeloid neoplasms." (PMID 40681596, 2025). "Even if diagnostic criteria are well specified in the WHO classification, in clinical practice, distinguishing aCML from the other BCR/ABL1 negative myeloid neoplasms could be challenging." (PMID 34684141, 2021).
non-small cell lung carcinoma (18 papers, 2013 to 2025). A group of at least three distinct histological types of lung cancer, including non-small cell squamous cell carcinoma, adenocarcinoma, and large cell carcinoma. "Despite the excellent finding of tyrosine kinase-targeted therapy for cancer treatment, such as imatinib for CML with BCR/ABL or erlotinib for non-small-cell lung carcinoma, the resistance to the treatment still remains a difficult problem and there is a need to overcome it to get better healthcare." (PMID 34068907, 2021). "Examples include the BCR::ABL1 gene fusion in patients with CML and ALK fusions (e.g. EML4::ALK) in non-small-cell lung cancer." (PMID 41421967, 2025). "Classic examples include gefitinib inhibition of EGFR mutant kinase in non-small cell lung cancer (NSCLC) and imatinib inhibition of BCR-ABL fusion kinase in chronic myeloid leukemia." (PMID 26078337, 2015).
acute promyelocytic leukemia (17 papers, 2013 to 2025). An aggressive form of acute myeloid leukemia (AML), characterized by arrest of leukocyte differentiation at the promyelocyte stage, due to a specific chromosomal translocation t(15;17) in myeloid cells. "Aside from those patients with chronic myeloid leukemia (CML) induced by wild-type BCR-ABL fusion protein or those with acute promyelocytic leukemia (APL) caused by reciprocal chromosomal translocation of the retinoic acid receptor α (RARα) gene, most patients have a poor prognosis." (PMID 29312995, 2017). "Furthermore, the combination treatment also inhibited the expression of breakpoint cluster region protein–acute promyelocytic leukemia (BCR/ABL), in which imatinib monotherapy was unable to do so." (PMID 34299604, 2021). "For example, chronic myelogenous leukemia (CML) is characterized by the Philadelphia chromosome and the resulting BCR/ABL1 gene fusion, while acute promyelocytic leukemia (APL) is characterized by RARA rearrangement." (PMID 23637631, 2013). "Examples in this respect are BCR::ABL and PML::RAR found in chronic myeloid leukemia (CML) and acute promyelocytic leukemia (APL) respectively." (PMID 40979168, 2025). "Importantly, PCR assays have been developed for three AML phenotypes: (i) acute promyelocytic leukemia (APL) (fusion gene PML::RARA); (ii) patients with NPM1 and CBF–AML (RUNX1::RUNX1T1 and CBFB::MYH11); and (iii) AML with fusion genes BCR::ABL1, KMT2::MLLT3, and DEK::NUP214." (PMID 37345204, 2023).